MTCH2 (mitochondrial carrier 2)
Diseases named in the same sentence as MTCH2 in open-access papers (continued):
Sharing a sentence is not in itself a finding about the gene and the disease.
glioma (continued). "Consistently, data from CGGA confirmed that MTCH2 expression was positively associated with tumor grade, IDH wildtype and 1p/19q non-codeletion in Chinese glioma population, supporting the notion that MTCH2 expression is correlated with glioma malignancy." (PMID 33509092, 2021). "All these data support that silencing MTCH2 in glioma cells impairs cell migration through multiple cellular mechanisms." (PMID 33509092, 2021). "We found that MTCH2 knockdown decreased the fluorescence intensity of F-actin in A172 cells, suggesting that MTCH2 knockdown impairs the cytoskeleton dynamics in glioma cells that is required for tumor migration." (PMID 33509092, 2021). "A common feature of glioma is the diffused tumor migration/invasion, and therefore we first evaluated the effect of MTCH2 knockdown on the suppression of glioma cell migration/invasion." (PMID 33509092, 2021). "Biochemical investigations of mitochondrial and cellular signaling alternations were performed to detect the mechanism by which MTCH2 regulates glioma malignancy." (PMID 33509092, 2021). "Taken together, all these results reveal that MTCH2 is required for the migration and invasion of glioma cells." (PMID 33509092, 2021). "Silencing of MTCH2 in glioma cells reduced cell migration/invasion and rendered cells more susceptible to apoptosis induced by temozolomide." (PMID 33509092, 2021). "Our work establishes the relationship between MTCH2 expression and glioma malignancy, and provides a potential target for future interventions." (PMID 33509092, 2021). "Moreover, knocking down MTCH2 in various glioma cell lines (A172 and U87MG) resulted in reduced migration/invasion." (PMID 39906820, 2025). "Silencing MTCH2 expression impairs cell migration and invasion of human glioma cells." (PMID 33509092, 2021). "Consistent with this notion, our findings expand current knowledge of MTCH2 in human gliomas." (PMID 33509092, 2021). "Therefore, we conclude that MTCH2 is highly expressed in human gliomas and its expression reciprocally correlates with patient survival." (PMID 33509092, 2021). "To further explore the role of MTCH2 in glioma invasion, we performed transwell Matrigel invasion assay to examine whether MTCH2 knockdown inhibits the invasion of glioma cells." (PMID 33509092, 2021). "Consistent with the fact that MTCH2 expression increased in glioma tissues, Kaplan–Meier survival analysis for multiple human glioma datasets (TCGA and CGGA) showed that patients with lower MTCH2 expression displayed significantly better overall survival than those with higher MTCH2 expression." (PMID 33509092, 2021). "In summary, all these findings support the notion that MTCH2 is highly expressed in glioma cells, and may inhibit mitochondrial OXPHOs in glioma cells." (PMID 33509092, 2021). "To further investigate the correlation of MTCH2 expression with clinical features in glioma, we performed an in silico analysis using gene expression and associated clinical data of glioma cohorts from two independent publicly available datasets, TCGA and CGGA." (PMID 33509092, 2021). "Based on the finding that MTCH2 expression is positively correlated with glioma malignancy, we asked whether MTCH2 functionally promotes gliomagenesis." (PMID 33509092, 2021). "To further address the question that whether MTCH2 knockdown increases mitochondrial respiratory function in glioma cells, here, we compared expression profiles of the respiratory chain complexes using the OXPHOs antibody cocktail (ab110413, Abcam) by Western blot." (PMID 33509092, 2021). "Silencing MTCH2 expression may increase mitochondrial OXPHOs in human glioma cells." (PMID 33509092, 2021). "Therefore, we propose that altered gene expression (not genomic mutation) of MTCH2 is the major way to regulate glioma malignancy." (PMID 33509092, 2021).
glioma (continued). "MTCH2 silencing disrupted mitochondrial functions, induced oxidative damage, hindered cell migration/invasion, inhibited pro-survival AKT signaling, and increased temozolomide sensitivity in glioma cells." (PMID 39910035, 2025). "We further found the MMP-9 mRNA was partially reduced by MTCH2 knockdown, indicating that the reduced MMP-9 expression may contribute to the decreased invasion activity of glioma cells." (PMID 33509092, 2021). "We found that MTCH2 expression was exceedingly associated with IDH wildtype and 1p/19q non-codeletion group, which indicates poor glioma prognosis." (PMID 33509092, 2021).
Alzheimer disease (5 papers, 2014 to 2025). A progressive, neurodegenerative disease characterized by loss of function and death of nerve cells in several areas of the brain leading to loss of cognitive function such as memory and language. "Several genome-wide association studies have related the MTCH2 locus with Alzheimer’s disease (AD), suggesting that MTCH2 deregulation can contribute to the pathogenesis of the disease." (PMID 28276496, 2017). "Mitochondrial Carrier Homolog 2 (MTCH2) is a novel regulator of mitochondria metabolism, which was recently associated with Alzheimer’s disease." (PMID 28276496, 2017). "Genes identified by our method suggest putative roles of several biological processes in Alzheimer’s disease, including mitochondrial dysfunction (indicated by UQCR11, MTCH2 and TMEM135), cholesterol transportation (indicated by TMEM135 and OSBP), and neuron activity (indicated by ADRA1A)." (PMID 33137096, 2020).
breast carcinoma (5 papers, 2021 to 2025). "A existing evidence showed that association between miRNA and MTCH2 is responsible for the development of breast cancer." (PMID 39906820, 2025). "Similarly, MTCH2, encoded by the SLC25A50 gene, is upregulated in malignant glioma, gastric cancer, and breast cancer where it promotes cell proliferation, invasion, migration, and cell cycle progression." (PMID 39795950, 2024). "MTCH2 expression is also elevated in breast cancer, promoting cell proliferation and advancing cell cycle progression via the PI3K-Akt pathway." (PMID 39948081, 2025). "Previous studies examined the role of MTCH2 in several types of tumors, including mammary carcinomas and acute myeloid leukemia (AML)." (PMID 33509092, 2021). "For example, MTCH2 was down-regulated in ErbB2-driven mammary carcinoma, and its induction reduced tumorigenicity and leads to growth arrest of breast cancer." (PMID 33509092, 2021). "Intriguingly, the role of MTCH2 in these tumors were opposite in breast cancer and AML." (PMID 33509092, 2021).
leukemia (4 papers, 2016 to 2024). A malignant (clonal) hematologic disorder, involving hematopoietic stem cells and characterized by the presence of primitive or atypical myeloid or lymphoid cells in the bone marrow and the blood. "The exceptional responders for PHLPP1 and MTCH2 are over-represented by cells from leukemia/lymphoma and colorectal cancer respectively (P = 2.211E-8 and 5.178E-3)." (PMID 27296290, 2016). "MTCH2 uses membrane-embedded hydrophilic residues to function as a gatekeeper for the outer membrane, controlling mislocalization of TAs into the endoplasmic reticulum and modulating the sensitivity of leukemia cells to apoptosis." (PMID 36264797, 2022).
malignant glioma (4 papers, 2021 to 2024). A grade III or grade IV glioma arising from the central nervous system. "MTCH2 (mitochondrial carrier homolog 2) has been reported to play a critical role in tumor invasion in malignant glioma." (PMID 38027033, 2023). "In summary, our work identifies the role of MTCH2 in malignant gliomas." (PMID 33509092, 2021). "In this study, we reveal the novel function of MTCH2 in malignant glioma." (PMID 33509092, 2021). "Our study demonstrates that MTCH2 is highly expressed in malignant gliomas." (PMID 33509092, 2021). "However, the role of MTCH2 in malignant glioma is not defined." (PMID 33509092, 2021).
glioblastoma (3 papers, 2021 to 2025). The most malignant astrocytic tumor (WHO grade IV). "The MTCH2 gene mutation was predicted to be highly deleterious; however, its mutation frequency in glioblastoma TCGA data was significantly low (~0.6%)." (PMID 36980325, 2023). "Herein, MTCH2 (Chr11: 47647265 A>G) gene mutation was identified to be potentially associated with highly progressive glioblastoma." (PMID 36980325, 2023). "The MTCH2 (Chr11: 47647265 A>G) gene mutation, predicted to be deleterious, was the only one that was common across the five samples, and may likely be associated with the rapid progression of glioblastomas." (PMID 36980325, 2023). "Thus, it is unclear whether to implicate or neglect the role of the given MTCH2 gene mutation in the progression of aggressive glioblastoma, in particular when the datasets assessed through cBioPortal included only those from primary tumor patients." (PMID 36980325, 2023). "Additionally, the mechanism involved in the possible association of MTCH2 gene mutation to aggressive glioblastoma may be investigated using mutant model systems for a better understanding." (PMID 36980325, 2023). "A substitution of A > G in the MTCH2 gene at Chr11: 47647265 was identified as potentially deleterious in highly aggressive glioblastoma." (PMID 39906820, 2025). "We next conducted a knockdown strategy using small interfering RNA (siRNA) to reduce MTCH2 expression in A172 human glioblastoma cells." (PMID 33509092, 2021). "The study herein is of a small sample size, hence the lack of statistical significance to implicate the role of MTCH2 gene mutation in aggressive glioblastoma." (PMID 36980325, 2023).
Insulin resistance (3 papers, 2016 to 2025). Increased resistance towards insulin, that is, diminished effectiveness of insulin in reducing blood glucose levels. "The involvement of Mimp/Mtch2 in diabetes is supported by a SNP in Mimp/Mtch2 gene which is correlated with increased insulin resistance and with increased cardiovascular disease risk in women with preexisting type 2 diabetes." (PMID 27359329, 2016). "In our study, the enhanced BAT thermogenesis and scWAT beige observed with adipose deletion of Mtch2 was linked to greater heat production, increased whole‐body energy expenditure, and improved hepatic steatosis and insulin resistance under energy‐excess conditions." (PMID 40051328, 2025). "Mimp/Mtch2 alters lipid metabolism and may play a role in the onset of obesity and development of insulin resistance." (PMID 27359329, 2016). "In human visWAT, we observed a positive correlation of MTCH2 expression (visMTCH2) with BMI, body fat, fasting plasma insulin (FPI), leptin, homeostatic model assessment for insulin resistance (HOMA-IR), and HDL-cholesterol." (PMID 41044057, 2025).
lung adenocarcinoma (3 papers, 2017 to 2025). A carcinoma that arises from the lung and is characterized by the presence of malignant glandular epithelial cells. "We began our investigation by accessing the The Cancer Genome Atlas Lung adenocarcinoma (TCGA-LUAD) database to gather MTCH2 expression data." (PMID 39948081, 2025). "CELF1 has been found involved in previous fusions with five different partners: with MTCH2 and MYOM1 in SCC and adenocarcinoma of the lung, respectively; with LUZP2 and ARFGAP2 in adenocarcinoma of the breast; and with BBOX1 in grade I-II astrocytoma of the brain." (PMID 28186972, 2017).
melanoma (3 papers, 2024 to 2025). A malignant, usually aggressive tumor composed of atypical, neoplastic melanocytes. "Based on bioinformatic analysis and experimental validation, this study identified mitochondrial carrier homolog 2 (MTCH2) as a key regulator of melanoma proliferation." (PMID 40204724, 2025). "Interestingly, recent outcomes placed MTCH2 as a key regulator of melanoma proliferation." (PMID 41227324, 2025). "These recent findings elucidate a mechanistic link between MTCH2 and the NRF2-RRM1 axis in melanoma proliferation, highlighting potential therapeutic targets for intervention." (PMID 41227324, 2025). "MTCH2 appears to enhance the expression and nuclear translocation of NRF2, which in turn increases RRM1 expression and promotes melanoma cell proliferation." (PMID 41227324, 2025). "Mechanistically, MTCH2 enhanced the expression and nuclear translocation of nuclear factor (erythroid-derived-2)-like 2 (NRF2), which up-regulated ribonucleotide reductase subunit M1 (RRM1) expression, thereby promoting melanoma cell proliferation." (PMID 40204724, 2025). "It was found that in resistant melanoma cell lines, the expression of the proapoptotic proteins BAX and MTCH2 were negatively or not correlated to cPARP levels." (PMID 39596009, 2024).
osteosarcoma (3 papers, 2024 to 2025). A usually aggressive malignant bone-forming mesenchymal neoplasm, predominantly affecting adolescents and young adults. "In line with our findings, another report examined the interaction mechanism between APOC1 and mitochondrial carrier homolog 2 (MTCH2) in osteosarcoma." (PMID 39511608, 2024). "The evidence indicated significant upregulation of APOC1 and MTCH2 expression in osteosarcoma SAOS-2 cells." (PMID 39511608, 2024). "Recent studies have found that APOC1 promotes osteosarcoma progression through binding to MTCH2, and preoperative APOB/APOA1 has been identified as an independent prognostic factor for osteosarcoma in children and adolescents." (PMID 38212768, 2024).
colorectal cancer (2 papers, 2016 to 2025). A primary or metastatic malignant neoplasm that affects the colon or rectum. "While the mitochondrial carrier homolog 2 (MTCH2) is implicated in lipid homeostasis and mitochondrial metabolism, its role in ferroptosis and colorectal cancer (CRC) remains uncharacterized." (PMID 40600459, 2025). "This study identifies MTCH2 as a crucial regulator of ferroptosis in colorectal cancer (CRC) progression." (PMID 40600459, 2025).
gastric cancer (2 papers, 2008 to 2024). A primary or metastatic malignant neoplasm involving the stomach. "To directly demonstrate the functional role of PGC genes in cellular invasion, we performed siRNA experiments where five PGC genes (p53CSV, MAP3K11, MTCH2, CPSF6, SKIP) were silenced in poorly-metastatic AGS gastric cancer cells." (PMID 18636107, 2008).
type 2 diabetes (2 papers, 2020 to 2025). "At the MTCH2 (rs10838738) locus, both AA (57.1%) and GG (19.1%) genotypes were most abundant in patients with overweight and type 2 diabetes." (PMID 32228543, 2020). "Furthermore, type II diabetes was associated with SLC16A11, SLC30A8, SLC39A11 and MTCH2." (PMID 40355757, 2025). "After adjusting for sex and age, loci near TMEM18 (rs6548238) and FAIM2 (rs7138803), but not SH2B1 (rs7498665), near GNPDA2 (rs10938397), MTCH2 (rs10838738) and near MC4R (rs12970134), were associated with increased risk for type 2 diabetes in obese individuals." (PMID 32228543, 2020).
acute myeloid leukemia (1 paper, 2021). Acute myeloid leukemia (AML) is a group of neoplasms arising from precursor cells committed to the myeloid cell-line differentiation. "A recent study showed the function of MTCH2 in acute myeloid leukemia (AML)." (PMID 33509092, 2021).
cognitive deficit (1 paper, 2017). "One of the early symptoms of AD is loss of memory, and in this study, we indeed found that MTCH2 deficiency in the forebrain leads to hippocampal-dependent cognitive deficits already in young mice, which correlated with a reduction in synaptic connectivity and an impaired hippocampal LTP." (PMID 28276496, 2017). "Taken together, mice deficient in forebrain MTCH2 display a hippocampal-dependent cognitive deficit, which may stem from impaired hippocampal LTP and synaptic connectivity." (PMID 28276496, 2017).
colitis (1 paper, 2025). Inflammation of the colon. "Moreover, we assessed the association between the MTCH2 expression and colitis using public databases." (PMID 40600459, 2025). "MTCH2 mRNA levels remained unchanged in DSS‐treated colitis mice compared to the untreated control mice (GSE244377, GSE252812, and GSE247433)." (PMID 40600459, 2025).
colon adenocarcinoma (1 paper, 2025). "MTCH2 staining was obviously higher in both colon adenocarcinoma (COAD) and rectum adenocarcinoma (READ) tissues than in normal tissues." (PMID 40600459, 2025).
colon cancer (1 paper, 2021). "In order to exclude the possibility that apoptosis-induced MOMP contributed to any effects observed, Ca2+-mediated mitochondrial injury was induced in Bax/Bak double-deficient human HCT116 colon cancer cells silenced for Mtch2." (PMID 34708044, 2021). "First, we demonstrated that, in a non-neuronal system, such as the human HCT116 colon cancer cells, MTCH2 is essential for Ca2+-induced mPTP opening and collapse of mitochondrial energetics." (PMID 34708044, 2021).
depression (1 paper, 2024). "The mitochondrial carrier homolog 2 (MTCH2) was the most significant candidate gene between depression and HEM." (PMID 39588545, 2024). "MYT1L, CELF4 and MTCH2 were given priority as novel pleiotropic genes between depression and HEM." (PMID 39588545, 2024). "MTCH2 (P adjust = 1.08E-11) was the most significant gene between depression and HEM, and it was also a mapped gene for one of the shared loci identified in the previous colocalization analysis between depression and HEM." (PMID 39588545, 2024).
Hyperglycemia (1 paper, 2025). An increased concentration of glucose in the blood. "Here, the induction of Gfra1 and Nrg1 may reflect adaptive metabolic or growth-factor signaling in response to hyperglycemia, whereas decreased expression of Aspdh and Mtch2 suggests compromised mitochondrial function and heightened oxidative challenges." (PMID 40920692, 2025).
lung carcinoma (1 paper, 2025). "First, the comparative mRNA expression levels of MTCH2 were examined in the normal lung cell line BEAS-2B alongside the lung cancer cell lines PC9, A549, and H1299." (PMID 40510359, 2025).
lung squamous cell carcinoma (1 paper, 2025). "Furthermore, data from The Cancer Genome Atlas for lung squamous cell carcinoma (TCGA-LUSC) indicated increased MTCH2 mRNA levels in LUAD tissues." (PMID 39948081, 2025).
lymph node metastasis (1 paper, 2025). "MTCH2 levels are also significantly higher in LUAD tissues with N2/N3 lymph node metastasis compared to those with N0 or N1 lymph node metastasis." (PMID 39948081, 2025).
metabolic syndrome (1 paper, 2016). A cluster of metabolic risk factors for CARDIOVASCULAR DISEASES and TYPE 2 DIABETES MELLITUS. "Several of these features are influenced by Mimp/Mtch2, tempting us to speculate that Mimp/Mtch2 plays a role in the onset and development of metabolic syndrome." (PMID 27359329, 2016).
prostate adenocarcinoma (1 paper, 2025). "We initiated our study by querying The Cancer Genome Atlas Prostate Adenocarcinoma (TCGA-PRAD) database to obtain MTCH2 expression data." (PMID 39910035, 2025).